RIT1 (Ras like without CAAX 1)
Diseases named in the same sentence as RIT1 in open-access papers (continued):
Sharing a sentence is not in itself a finding about the gene and the disease.
liver cancer (1 paper, 2023). An epithelial or non-epithelial malignant neoplasm that arises from the liver. "Knockdown of NECAB3 suppressed aggressive phenotype of liver cancer via modulating the HIF-1α/RIT1 axis, providing a possible target for liver cancer therapy." (PMID 37215053, 2023). "Then, functional experiments revealed that downregulation of NECAB3 suppressed liver cancer cell migration and overexpression of RIT1 promoted cell migration (P < 0.05)." (PMID 37215053, 2023). "Knockdown of NECAB3 suppressed the aggressive phenotype of liver cancer via modulating the HIF-1α/RIT1 axis, providing a possible target for liver cancer therapy." (PMID 37215053, 2023). "Consistent with the conjecture, results revealed that the inhibitory effect of downregulation of NECAB3 on liver cancer migration and invasion was reversed by the overexpression of RIT1." (PMID 37215053, 2023). "As expected, it was observed that overexpression of NECAB3 enhanced liver cancer cell migration and invasion, which was suppressed by downregulation of RIT1 (P < 0.05)." (PMID 37215053, 2023). "In other words, NECAB3 regulated liver cancer migration and invasion through modulating RIT1." (PMID 37215053, 2023). "Furthermore, NECAB3 regulated liver cancer migration and invasion through modulating RIT1 expression." (PMID 37215053, 2023). "Given the evidence, we speculated that NECAB3 might regulate liver cancer progression via modulating the HIF-1α/RIT1 axis." (PMID 37215053, 2023). "Additionally, knockdown of NECAB restrained liver cancer cell invasion and overexpression of RIT1 promoted cell invasion (P < 0.05)." (PMID 37215053, 2023). "Therefore, we inferred that the upregulated NECAB3 might regulate liver cancer progression via modulating the HIF-1α/RIT1 axis." (PMID 37215053, 2023). "Furthermore, in liver cancer, HIF-1α has been shown to modulate cancer growth and metastasis and cell sensitivity to Sorafenib through inducing Ras like without CAAX 1 (RIT1) expression." (PMID 37215053, 2023).
lymphatic disorders (1 paper, 2025). "Our review of 14 patients with NS exhibiting RIT1 mutations revealed that all patients presented with lymphatic disorders during the fetal and neonatal periods." (PMID 41388936, 2025). "Other groups have reported that patients with NS harboring an RIT1 mutation frequently exhibit prenatal or neonatal abnormalities associated with cardiovascular and lymphatic disorders." (PMID 41388936, 2025).
lymphoma (1 paper, 2020). A malignant (clonal) proliferation of B- lymphocytes or T- lymphocytes which involves the lymph nodes, bone marrow and/or extranodal sites. "A previous study reported an association between RIT1 gene inactivation and lymphoma progression." (PMID 33168059, 2020).
mitral valve prolapse (1 paper, 2025). A fairly common and often benign valvular heart disorder characterized by redundancy or hooding of mitral valve leaflets so that they prolapse into the left atrium, often causing mitral regurgitation. "We more frequently identified ASD (n = 3, 75%) with PTPN11 variants and variable cardiac conditions, including mitral valve prolapse (n = 2, 50%) and tricuspid regurgitation (n = 1, 25%), with RIT1 variants." (PMID 40467618, 2025).
muscle atrophy (1 paper, 2020). The loss of muscle tissue due to inactivity or disease. "In summary, we identified miR‐29b‐3p as a muscle atrophy‐associated exosomal miRNA with potential to be uptake by neuronal cells which consequently inhibits neuronal cell differentiation via targeting the mRNAs of c‐FOS, BCL‐2, RIT1, LAMC1, and upregulation of lncRNA HIF1α‐AS2." (PMID 32233025, 2020).
neuroblastoma (1 paper, 2018). Neuroblastoma (NB) is the most common solid, extracranial childhood tumor. "However, we could not detect any effect of the RIT1 mutants on AKT phosphorylation levels downstream of PI3K that is in line with previous experiments, in which expression of Rit1 in PC6 cells and the human neuroblastoma cell line SH-SY5Y did not induce AKT activation." (PMID 29734338, 2018).
pheochromocytoma (1 paper, 2017). "This is complicated by the fact that while activation of a SOS/Shc-Grb2 complex has been associated with in vitro RIT1 activation following either NGF or PCAP stimulation of pheochromocytoma cells, biochemical analysis has yet to identify a bona fide RIT1GEF." (PMID 28607354, 2017).
prostate carcinoma (1 paper, 2026). A carcinoma that arises from epithelial cells of the prostate gland. "This analysis identified CASP3, XRCC2, and RIT1 transcripts in circulating EVs as promising biomarkers for the early detection of significant prostate cancer." (PMID 41885368, 2026).
Pulmonary lymphangiectasia (1 paper, 2022). Abnormal dilatation of the pulmonary lymphatic vessels. "Patients with PTPN11-mutations showed a slightly higher rate of pulmonary lymphangiectasia during infancy than patients with RIT1-mutations who showed a higher prevalence of peripheral/genital edema." (PMID 35778409, 2022).
pulmonary valve dysplasia (1 paper, 2022). "Patients with RIT1 mutation were characterized by pulmonary valve dysplasia with stenosis and ASD/PFO." (PMID 35770001, 2022). "RIT1 mutations predispose patients to both HCM and valve abnormalities, while our findings related to cardiac malformation were pulmonary valve dysplasia with stenosis, ASD and PFO." (PMID 35770001, 2022).
triple-negative breast carcinoma (1 paper, 2019). An invasive breast carcinoma which is negative for expression of estrogen receptor (ER), progesterone receptor (PR), and human epidermal growth factor receptor 2 (HER2). "Results showed that RIT1 expression was higher (p<0.05) in triple negative breast cancer and high grade ovarian cell lines than in the other cell lines; PSAT1 expression is significantly higher in triple negative breast cancer cell lines (p<0.001) as compared to the other breast cell lines." (PMID 31105872, 2019).
cancer (17 papers, 2014 to 2026). A tumor composed of atypical neoplastic, often pleomorphic cells that invade other tissues. "RIT1 gene mutations display a close connection with tumour occurrence and development, especially in some malignant tumours, showing an important carcinogenic effect." (PMID 39833023, 2025). "Mutations in RIT1 usually occur in the early stages of cancer and are driver mutations that can activate downstream signalling pathways to promote cell proliferation, migration, metastasis and anti‐apoptosis." (PMID 39833023, 2025). "We recently performed transcriptome and proteome profiling of human lung epithelial cells ectopically expressing oncogenic KRAS and another cancer-associated Ras GTPase, RIT1." (PMID 36522653, 2022). "Our previous work found that cancer- and Noonan-associated RIT1 variants such as RIT1M90I can transform NIH3T3 fibroblasts to a phenotype reminiscent of RAS-transformed cells." (PMID 34373451, 2021). "In both cancer and NS, a similar spectrum of RIT1 missense and in-frame insertion/deletion mutations is observed, with the majority occurring in the switch II domain of the protein." (PMID 34373451, 2021). "RIT1 is the most upregulated RAS subfamily member in LZTR1 deficiency in several cancer types." (PMID 37626065, 2023). "Accordingly, EGF-induced ERK activation has previously been found to be enhanced and/or sustained in T-REx293T cells expressing NS-associated RIT1 mutants, and ectopic expression of NS- and cancer-related RIT1 mutants in PC6 cells induced phosphorylation of both MEK and ERK." (PMID 29734338, 2018). "Since stemness of cancer has been indicated to be associated with drug resistance, we further studied whether RIT1 expression affects the stemness of ESCC." (PMID 30348939, 2018). "Because mTORC2 inhibitors are in development for the treatment of cancer, our findings suggest that specifically targeting p38-mTORC2 signaling could represent a therapeutic strategy for RIT1-mutated tumors." (PMID 25531880, 2014). "Similarly, EGF-induced ERK activation was previously found to be enhanced and/or sustained in T-REx293T cells expressing NS-associated RIT1 mutants, and ectopic expression of NS- and cancer-related RIT1 mutants in PC6 cells induced phosphorylation of both MEK and ERK." (PMID 29734338, 2018). "RIT1 is a member of the Ras superfamily of small GTPases, and it functioned as oncogenic protein in cancer development." (PMID 37215053, 2023). "Therefore, the role of RIT1 in cancer development remains controversial and requires specific analysis based on specific tissue types." (PMID 39833023, 2025). "Pharmacological RAF inhibition abolished MAPK activation induced by ectopic RIT1 expression, including RIT1Q79L (a constitutively active mutant analogous to RASQ61L), and a panel of NS and cancer-associated variants with variable levels of GTP-loading in cells." (PMID 37450595, 2023). "In addition, RIT1 moonlights as a mitotic checkpoint regulator, among other functions, imparting mutant RIT1 cancer cells with unique therapeutic vulnerabilities." (PMID 37450595, 2023). "Cancer- and NS-associated variants also display decreased GTP hydrolysis, increased nucleotide exchange, or increased GTP binding, and the exact contribution of GTP binding versus protein abundance to RIT1’s oncogenic function remains to be determined." (PMID 34373451, 2021). "This is particularly interesting because NTRK1 is a membrane-bound receptor that phosphorylates itself and members of the MAPK pathway and it is already known that it confers resistance to cancer chemotherapy by activating p38 mitogen-activated protein kinase signaling pathways, where RIT1 belongs." (PMID 31105872, 2019). "RIT1 activation can also regulate cell survival and metabolism via PI3K/AKT signalling, making cancer cells more adaptable and anti‐apoptotic." (PMID 39833023, 2025).
cancer (continued). "Together, these data show that Hippo inactivation synergizes with mutant RIT1 in cancer models, and Hippo pathway inactivation and YAP1 activation also occurs in RIT1-altered human lung tumors." (PMID 34373451, 2021). "In conclusion, our study indicates for the first time that RIT1 displays tumor-suppressing functions in ESCC, and these functions were carried out by inhibiting MAPK and PI3K/AKT signaling pathway, inhibiting EMT, and downregulating cancer stemness of ESCC cells." (PMID 30348939, 2018).
tumor (13 papers, 2017 to 2025). "Because of the carcinogenic effect of RIT1 mutations in certain tumours, inhibiting its function may become a new treatment strategy." (PMID 39833023, 2025). "Collectively, RIT1 overexpression significantly diminishes cellular apoptosis and facilitates tumour progression in vitro and in vivo." (PMID 39833023, 2025). "Overall, these findings indicate that RIT1 facilitates tumour progression by activating PI3K/AKT/c‐Myc signalling." (PMID 39833023, 2025). "Aiming at further clarifying the RIT1 effect on tumour cell proliferation, we used CCK8, clone formation assay, TUNEL and EdU assay to verify." (PMID 39833023, 2025). "There are also reports indicating that the role of RIT1 in cytoskeleton reorganisation can enhance cell migration and invasion capabilities and promote tumour metastasis." (PMID 39833023, 2025). "The RIT1 mutations have been reported to promote cell proliferation and survival via Ras‐MAPK/ERK signalling whose activation is crucial in tumour occurrence and development." (PMID 39833023, 2025). "The RIT1 has been shown to affect the function of CD8+ T cells in the tumour microenvironment, but its specific mechanism is still under exploration." (PMID 39833023, 2025). "SMC3 knockdown also reversed the tumor-promoting effects of RIT1 in vivo in mouse subcutaneous tumor experiments." (PMID 38017479, 2023). "In this study, we found that the expression of RIT1 is downregulated in ESCC compared to corresponding non-tumor tissues." (PMID 30348939, 2018). "To further confirm the oncogenic role of RIT1 in vivo, we established a xenograft tumor mouse model by subcutaneously injecting RIT1-knocked-down KYSE150 and ECa109 cells into the right dorsal flanks of a group of 8 nude mice, respectively." (PMID 30348939, 2018). "Taken all together, our results indicated that RIT1 inhibited tumor tumorigenesis and metastasis via inhibiting MAPK and PI3K/AKT pathways and EMT in ESCC, respectively." (PMID 30348939, 2018). "The diminished expression of Ki‐67 in xenograft tumours within the c‐Myc silencing cohorts suggests that the silencing of c‐Myc may effectively mitigate the impact of RIT1 on cell proliferation." (PMID 39833023, 2025). "Furthermore, Western blot result showed that shNECAB3 greatly suppressed the protein levels of NECAB3, HIF-1α, and RIT1 in tumor tissues (P < 0.001)." (PMID 37215053, 2023). "Our study also found that RIT1 inhibited tumor invasion and metastasis." (PMID 30348939, 2018). "Results showed that RIT1 inhibited tumor growth and proliferation." (PMID 30348939, 2018). "All outcomes manifested that RIT1 overexpression could enhance tumour cell proliferation." (PMID 39833023, 2025). "Acetylation protection of SMC3 by RIT1 during mitosis may partially rescue mitotic errors caused by the negative regulation of SAC by RIT1, thereby ensuring efficient division and proliferation of tumor cells to drive tumor progression." (PMID 38017479, 2023). "Drugs targeting RIT1 downstream signalling pathways (MAPK/ERK and PI3K/AKT) have shown effects in some tumours." (PMID 39833023, 2025). "High expression of RIT1, a significant degradation target of the RAS subfamily by the CUL3-LZTR1 complex, induces epithelial-mesenchymal transition (EMT), an early step in tumor metastasis in lung epithelial cells." (PMID 37626065, 2023). "Furthermore, to validate the role of RIT1 in promoting tumour growth by activating PI3K‐AKT signalling, RIT1 knockdown and overexpression experiments were conducted in T98G and A‐172 cell lines, respectively." (PMID 39833023, 2025). "RIT1 protects and maintains the acetylation of SMC3 through its interaction with PDS5, thereby ensuring rapid mitotic progression in HCC cells and promoting tumor progression." (PMID 38017479, 2023).
tumor (continued). "The average fold change of RIT1 mRNA was significantly lower in ESCC tumor tissues than those in paired non-tumor tissues (13.7- vs. 23.6-fold changes)." (PMID 30348939, 2018). "Expression of RIT1 was also investigated by immunohistochemistry (IHC) with a monoclonal RIT1 antibody using an ESCC tissue microarray containing 228 pairs of ESCC tumor and corresponding non-tumor tissues." (PMID 30348939, 2018). "Expression of RIT1 was tested by quantitative real-time PCR (qRT-PCR) and compared between tumor and paired non-tumor tissues in 96 ESCC cases." (PMID 30348939, 2018). "Since RIT1 low expression correlated with worse prognosis in ESCC patients, we speculated that RIT1 might act as a suppressing regulation factor in ESCC, and RIT1 expression may inhibit tumor cell growth." (PMID 30348939, 2018). "Although no RIT1, RRAS2, or MRAS mutations were found in the TCGA BC dataset, one tumor with undetermined ER and HER2 statuses harbored a RAC1 (P69S) mutation, and one TNBC tumor harbored a RHOB (D13Y) mutation." (PMID 28636652, 2017). "Whether RIT1 inhibits tumor invasion and metastasis via inhibiting EMT has not been studied." (PMID 30348939, 2018).
RIT1 also shares sentences with these, for which no sentence is quoted: lymphedema (3 papers); hydrops (2); infection (2); left ventricular hypertrophy (2); Splenomegaly (2); acute myeloid leukaemia (1); adrenocortical carcinoma (1); arteriovenous malformations (1); Ascites (1); brain trauma (1); cardiofaciocutaneous syndrome (1); cellulitis (1); cervical cancer (1); CHARGE syndrome (1); cutaneous melanoma (1); dysrhythmias (1); Dystonia (1); genetic disorder (1); hematologic disorder (1); hydrops fetalis (1); intestinal lymphangiectasia (1); lymphangiectasia (1); myeloproliferative disorder (1); neurodevelopmental disorder (1); neurological disorders (1); non-small cell lung carcinoma (1); Noonan syndrome 7 (1); pancreatic carcinoma (1); Pleural effusion (1); Polyhydramnios (1).
A further 7 diseases each share a sentence with RIT1 in 1 paper.